PAX7 (paired box 7)
Description:
Transcription factor that is involved in the regulation of muscle stem cells proliferation, playing a role in myogenesis and muscle regeneration.
Synonyms: HUP1; CMYO19; CMYP19; MYOSCO; PAX7B; RMS2
Tractability: No criterion of Open Targets' tractability assessment is met for any kind of drug.
Gene: Protein-coding gene on chromosome 1 (18,630,846 to 18,748,876, forward strand). Ensembl gene ENSG00000009709.
Subcellular location: Nucleus
Pathways (Reactome):
Developmental Biology: Specification of the neural plate border
Gene Ontology:
Molecular function: DNA-binding transcription factor activity; sequence-specific double-stranded DNA binding; DNA-binding transcription factor activity, RNA polymerase II-specific; RNA polymerase II cis-regulatory region sequence-specific DNA binding; DNA binding; sequence-specific DNA binding
Biological process: anatomical structure morphogenesis; negative regulation of apoptotic process; nervous system development; regulation of transcription by RNA polymerase II; skeletal muscle satellite cell differentiation; regulation of DNA-templated transcription
Cellular component: chromatin; nucleus
Genetic constraint (gnomAD): Loss-of-function variants: 16 observed, 48.21 expected, observed/expected ratio (o/e) 0.33, 90% interval 0.22 to 0.5. The upper end of that interval is the gene's LOEUF score, 0.5, which puts it in group 2 of 6, group 1 being the genes least tolerant of losing a copy. Missense variants: 637 observed, 710.85 expected, observed/expected ratio (o/e) 0.9, 90% interval 0.84 to 0.96. Synonymous variants: 308 observed, 291.6 expected, observed/expected ratio (o/e) 1.06, 90% interval 0.96 to 1.16.
Gene-disease validity (ClinGen):
ClinGen rates the evidence that PAX7 causes each of these diseases.
congenital myopathy with myasthenic-like onset (autosomal recessive): Moderate. Congenital myopathy with myasthenic-like onset is a rare, genetic, non-dystrophic myopathy characterized by fatigable muscle weakness associated with congenital myopathy.
Cancer hallmarks: proliferative signalling (promotes); invasion and metastasis (promotes)
Homologues: Orthologues: chimpanzee PAX7 (100% identical), dog PAX7 (99% identical), macaque PAX7 (99% identical), mouse Pax7 (97% identical), rat Pax7 (97% identical), guinea pig PAX7 (93% identical), pig PAX7 (93% identical), rabbit PAX7 (92% identical), tropical clawed frog pax7 (90% identical), zebrafish pax7a (88% identical), zebrafish pax7b (88% identical). Paralogues in human: PAX3 (73% identical), PAX5 (32% identical), PAX2 (31% identical), PAX8 (30% identical), PAX1 (27% identical), PAX4 (27% identical), PAX9 (26% identical), PAX6 (20% identical), ARX (18% identical), ALX4 (16% identical), NOBOX (16% identical), RAX (16% identical), and 38 more.
Diseases named in the same sentence as PAX7 in open-access papers:
PAX7 is named in the same sentence as 111 diseases in open-access papers, as found by Europe PMC text mining. Sharing a sentence is not in itself a finding about the gene and the disease. The quoted sentences say what the papers report.
rhabdomyosarcoma (39 papers, 2003 to 2026). A rare aggressive malignant mesenchymal neoplasm arising from skeletal muscle. "Our assay reported several diagnostic fusions, including PAX3 and PAX7 joining with FOXO1 in alveolar rhabdomyosarcoma and SS18-SSX fusion in synovial sarcomas." (PMID 40711866, 2025). "In rhabdomyosarcoma, Pten loss caused a less differentiated, more aggressive tumor dependent on PAX7 for not only the malignant phenotype but for rhabdomyosarcoma identity itself." (PMID 36830628, 2023). "Charville and collaborators suggest that significant expression of PAX7 is a unique feature of rhabdomyosarcoma and ES, and put forward PAX7 as a diagnostic marker for ES diagnosis." (PMID 33924679, 2021). "The alveolar rhabdomyosarcoma is characterized by the chromosomal translocation that fuses the PAX3 or PAX7 genes with the gene encoding the transcription factor FOXO1/FKHR." (PMID 25341037, 2014). "RH30 rhabdomyosarcoma subclones indicated pivotal role of transcription factors associated with myogenic differentiation, such as PAX7 and ID proteins, in the development of RMS that should be investigated in future with focus on molecular mechanisms of their action." (PMID 34440639, 2021). "Alveolar rhabdomyosarcoma (aRMS) is a pediatric soft tissue cancer commonly associated with a chromosomal translocation that leads to the expression of a Pax3:Foxo1 or Pax7:Foxo1 fusion protein, the developmental underpinnings of which may give clues to its therapeutic approaches." (PMID 28883017, 2017). "PAX3::FOXO1 fusion gene is detected in 85% of alveolar rhabdomyosarcoma, while PAX7::FOXO1 fusion gene is seen in 10%." (PMID 40666501, 2025). "Prior research has demonstrated the significance of PAX7 as a crucial transcription factor in muscle formation and its involvement in different types of cancer, notably rhabdomyosarcoma (RMS)." (PMID 40370330, 2025). "Alveolar rhabdomyosarcoma (ARMS)—an invasive subtype of rhabdomyosarcoma—is characterised by fusion of Pax3 or Pax7 genes on chromosome 1 and 2, respectively, with the FOXO1 gene; which encodes Pax3-FOXO1 and Pax7-FOXO1 fusion proteins." (PMID 38995522, 2024). "One key relationship between PTEN loss and tumor promoting transcriptional programs seen in rare cancers is the PTEN–PAX7 (Paired box 7) axis observed in both glioblastoma and rhabdomyosarcoma." (PMID 36830628, 2023). "Silenced PAX7 expression with siRNA in rhabdomyosarcoma cell line RH30 PAX7+ cells led to decreased proliferation of the factors ID1, -2, -3, and -4 and sine oculis-related homeobox (SIX1 and -4) but increased MyoD and MyoG." (PMID 34886282, 2021). "PAX7 is known to be expressed in ES, subsets of rhabdomyosarcoma, and rare cases of synovial sarcomas, though only in ES samples it was found positive in all evaluated cases." (PMID 33924679, 2021). "Sarcoma-specific fusion gene transcripts like EWSR1-ERG or EWSR1-FLI1 in EWS or PAX3-FKHR or PAX7-FKHR in alveolar rhabdomyosarcoma (aRMS) are providing a promising way to detect CTCs." (PMID 30326929, 2018). "Several clinical reports showed an abnormal high level of Pax7 in skeletal muscle tissue from patients with different cancers, including gastric and pancreatic tumors and rhabdomyosarcomas." (PMID 27034684, 2016). "The FOXO1 gene was particularly interesting since it is fused to either the PAX3 gene or the PAX7 gene in alveolar rhabdomyosarcoma." (PMID 25341037, 2014). "Of great interest, a miRNA signature was identified in rhabdomyosarcoma tumours from patients in accordance with the molecular translocation Pax3 or Pax7." (PMID 21437224, 2011). "Furthermore, ALK is expressed on the cell surface of rhabdomyosarcomas harboring a PAX3 or PAX7::FOXO1 fusion (fusion-positive rhabdomyosarcoma), the most common soft tissue sarcoma of childhood and adolescence." (PMID 40813394, 2025).
rhabdomyosarcoma (continued). "PAX3 and PAX7 chromosomal translocations define childhood rhabdomyosarcomas, raising the possibility that PAX2 gene rearrangements or deletions might analogously underpin PAX2 expression loss in EC." (PMID 40829174, 2025). "Multiple alternatively spliced isoforms may also be present at the same time, as is the case for PAX3 and PAX7 in the developing embryo and in rhabdomyosarcoma tumors." (PMID 38473380, 2024). "PAX7 is described to be expressed in ES, subsets of rhabdomyosarcoma, and rare synovial sarcomas." (PMID 33924679, 2021). "In each case, FOXO fusion proteins result from translocations generating chimeric transcripts encoding the N-terminal region of the fusion partner (MLL for the leukemias, and either PAX3 or PAX7 for the rhabdomyosarcomas), and the C-terminal portion of the FOXO component." (PMID 17442120, 2007). "Similarly, rhabdomyosarcoma can result from fusion of PAX7 and FOXO1 genetic materials." (PMID 38540335, 2024). "PAX-7 is transcriptionally required for the specific development of skeletal muscle stem cells and has been proven to be expressed in rhabdomyosarcoma, Ewing sarcoma and PDSS; however, the expression of PAX-7 remains unclear in other histological subtypes of SS17,22." (PMID 37193761, 2023). "For example, module 3 contained 139/331 genes upregulated in alveolar compared to embryonic rhabdomyosarcoma, 27/48 genes that were downregulated when FOXO1-PAX3 was altered with RNA interference, and 22/64 genes previously associated with cell line differences related to PAX3 and PAX7 fusions." (PMID 31480361, 2019). "Alveolar rhabdomyosarcoma (RMS), an aggressive pediatric soft tissue cancer, is driven by the oncogenic fusion transcription factor PAX3::FOXO1 (P3F) or PAX7::FOXO1." (PMID 41473312, 2025). "A similar phosphorylation event occurs at Ser203 in the PAX7 protein, another Group III PAX family member fused to FOXO1 in a subset of alveolar rhabdomyosarcoma." (PMID 38473380, 2024). "For example, alveolar rhabdomyosarcoma is characterized by consistent chromosomal translocations and chimeric genes, PAX3-FKHR and PAX7-FKHR, which are expressed as novel fusion transcripts." (PMID 38520005, 2024). "In alveolar rhabdomyosarcoma (ARMS), a chromosomal translocation fusing FOXO1 to either PAX3 or PAX7 is present in about 80% of cases." (PMID 38473380, 2024). "The alveolar subtype of rhabdomyosarcoma (ARMS) is typically characterized by a specific reciprocal chromosomal translocation involving the PAX3 and FKHR or PAX7 and FKHR genes, respectively." (PMID 26587222, 2015). "By miRNA profiling, we were able to discriminate the different subtypes of rhabdomyosarcoma: Pax3+ or Pax7+ or fusion negative, classically difficult to diagnose by histological analysis." (PMID 21437224, 2011). "Indeed, PAX7 appears to be essential for the rhabdomyosarcoma cell line RD, but not PAX3 (bottom row)." (PMID 30683138, 2019). "However, most of these genes from differentially co-expression fusion positive modules reported no known responses to PAX3 or PAX7 in rhabdomyosarcoma or other cancers." (PMID 31480361, 2019). "Rhabdomyosarcoma is subclassified by the presence or absence of a recurrent chromosome translocation that fuses the FOXO1 and PAX3 or PAX7 genes." (PMID 31480361, 2019). "Alveolar rhabdomyosarcoma was ruled out by negative myogenin and myoD1 and by absence of PAX3/PAX7-FKHR translocations by FISH." (PMID 20598147, 2010).
alveolar rhabdomyosarcoma (21 papers, 2010 to 2025). A rapidly growing malignant mesenchymal neoplasm. "Chromosomal translocations causing gene fusions between FKHR (Foxo1) and Pax3 or Pax7 are characteristic of alveolar rhabdomyosarcoma (ARMS), a pediatric soft tissue cancer derived from the muscle lineage." (PMID 33193700, 2020). "PAX3 and PAX7 are implicated in Alveolar Rhabdomyosarcoma (ARMS), a pediatric tumour of skeletal muscle origin that results from a translocation between PAX3/7 and FKHR (FOXO1A)." (PMID 23650549, 2013). "The prognostic relevance of PAX7::FOXO1‐positive and FN alveolar rhabdomyosarcoma (aRMS), along with the clinical factors described in this report, allows further refinement of risk assessment of patients with localized and metastatic (aRMS)." (PMID 39781573, 2025). "For example, in alveolar rhabdomyosarcoma (aRMS), the fusion oncogene PAX3::FOXO1 (or PAX7::FOXO1) binds SEs together with other MTFs, including MYOD, MYOG, and MYCN, to sustain proliferation, and their depletion leads to altered proliferation and cell death." (PMID 41444391, 2025).
Cachexia (11 papers, 2016 to 2026). Severe weight loss, wasting of muscle, loss of appetite, and general debility related to a chronic disease. "Significant co-upregulation of APOA2 and PAX7 was found in Black patients with localized disease, both linked to cachexia." (PMID 39580376, 2024). "The previous study revealed that cancer cachexia is associated with a proliferation of SCs by observing an elevated production of the satellite cell marker Pax7 in cachexia models." (PMID 39404384, 2024). "In cancer-induced cachexia, NF-κB expression is associated with Pax7 dysregulation and muscle wasting." (PMID 29041952, 2017). "Our findings showed that cachexia is linked to the overexpression of Pax7 in satellite cells and other myogenic precursors in both C26 colon carcinoma bearing mice and pancreatic cancer patients." (PMID 27034684, 2016). "By reacting to NF-κB, the capacity of stem cells to differentiate in the muscle milieu was impeded via the constant expression of Pax7, which prevented them from merging with injured myofibers, leading to exacerbating muscle atrophy in cachexia." (PMID 39404384, 2024). "Recently, a study using cancer-induced cachexia animal models showed PAX7 upregulation compared to controls, and voluntary wheel running of physical activity counteracted with PAX7 overexpression." (PMID 32698257, 2020). "We also measured the levels of PAX7, a transcription factor whose expression is sustained by NF-κB during C26-mediated cachexia, and those of myogenin, because the latter is known to induce atrogin-1." (PMID 32824440, 2020). "In contrast, our study found that NF-κB coincides with a decrease in Pax7 expression, suggesting that the function of NF-κB differs between a burn injury and cancer-induced cachexia." (PMID 29041952, 2017). "Deregulated levels of Pax7 have been recently shown to contribute to muscle wasting in cancer cachexia." (PMID 27034684, 2016). "Pax7 is one of the key mediators of the impaired myogenic ability observed in cancer-induced cachexia." (PMID 27034684, 2016). "Given the observed exercise-induced Pax7 downregulation to physiological levels in cachexia, we analyzed the effects of exercise on muscle homeostasis." (PMID 27034684, 2016). "Muscle regeneration is highly compromised in cachexia conditions, and proliferating Pax7+ve cells are unable to terminally differentiate (and to express myogenin) and fuse into myofibers because they are prevented by tumour‐derived factors influencing the muscle microenvironment." (PMID 32159297, 2020). "Interestingly, our findings reveal that NF-κB expression coincides with the reduction in muscle fiber cross-sectional area and the downregulation of Pax7 expression at 2 days post-burn, an occurrence that is similar to that in cancer-induced cachexia." (PMID 29041952, 2017). "In cancer-induced cachexia, NF-κB activation coincides with an increase in Pax7 expression." (PMID 29041952, 2017). "We tested whether physical activity, known to be able to rescue muscle homeostasis in cachexia, was also sufficient to restore Pax7 physiological expression levels and promote stem cell progression from myoblast to nascent myofibers." (PMID 27034684, 2016). "Intriguingly, non-myogenic cells were forced to express Pax7 (a muscle satellite cell marker) through NF-κB signaling in cachexic muscle, which was considered to be one mechanism underlying the impaired muscle regeneration in cachexia model mice." (PMID 30300394, 2018). "Compared to NI-control animals, in muscles of the two unloaded groups of animals and in the two LC-cachexia mice, myoblast (Pax-7+ and MyoD+) counts did not significantly differ, whereas the numbers of myocytes (MyoD+ and myogenin+) significantly decreased." (PMID 33142912, 2020). "Strikingly, PM01183 efficiently reduced PAX7 and myogenin levels, but it is unlikely that such drug completely resolves the myogenic impairment typical of cachexia, as suggested by the failure of PM to restore C/EBPβ to normal levels." (PMID 32824440, 2020).
Cachexia (continued). "With the aim to investigate the molecular signature of muscle response to cachexia and how it is modulated by exercise, we performed WB analysis for markers of muscle regeneration, such as MyoD and Pax7 in C26-bearing and control mice, with or without exercise." (PMID 27034684, 2016).
sarcopenia (11 papers, 2012 to 2025). Progressive decline in muscle mass due to aging which results in decreased functional capacity of muscles. "We found a decrease in the expression of HIF-1α and its target genes in sarcopenia, as well as of PAX7, the major stem cell marker of satellite cells, whereas the atrophy marker MURF1 was increased." (PMID 35806119, 2022). "Increased gene of Pax7 stimulation may contribute to the increase of regenerative potential of aged muscle, where the decrease of Pax7 pool correlated with sarcopenia." (PMID 30647761, 2018). "To optimize the TNF‐α treatment conditions for sarcopenia modelling, we first exposed hSkMOs to varying concentrations of TNF‐α (0, 5, 10, and 20 ng/mL) for 2 days and analysed the number of PAX7+ SCs by immunohistochemistry." (PMID 40810394, 2025). "qRT-PCR data showed that AK treatment increased the expression of not only Pax7 (muscle stem cells, not significant) but also Igf-1 (P < 0.05), which is involved in the hypertrophy of aged muscle, thereby supporting the potential of AK as a new candidate therapeutic agent for sarcopenia." (PMID 34906228, 2021).